CD4 (CD4 molecule)
Diseases named in the same sentence as CD4 in open-access papers (continued):
Sharing a sentence is not in itself a finding about the gene and the disease.
infection (continued). "Urease B subunit (UreB), a conserved protein of H. pylori, is capable of inducing specific CD4+ T-cell responses and provides protection against this infection." (PMID 26434384, 2015). "To determine the mechanism through which CD4+ T cells drive IEC proliferation during infection, we next examined levels of IL-22; a cytokine produced by CD4+ T cells during enteric infection that interacts with its receptors expressed by IEC." (PMID 26285214, 2015). "This suggests either that other subsets of CD4+ T cells can produce IL-21, or that Th1/Th2/Th17 subsets activated in infections can acquire an additional Tfh phenotype." (PMID 25763578, 2015). "Despite low viremia of circulating blood, the CD4 T cells in the LNs appear to undergo continuing infection suggesting a local source of virus." (PMID 26623655, 2015). "This heterogeneity is somewhat similar to results obtained by a study of human T cells, where, seven days after infection, a strong variation in the frequency of CD4+CD38+Ki-67+ and CD8+CD38+Ki-67+ T cells was observed between different individuals." (PMID 25971313, 2015). "Taken together, these data demonstrate a key CD4 T cell-intrinsic role of GITR during LCMV cl 13 infection, with the most dramatic effects on the Th1 and Tfh responses." (PMID 25590581, 2015). "In this study we investigated double infection of primary CD4+ T cells using reporter viruses expressing two distinct fluorescent proteins, EGFP and mCherry." (PMID 26559763, 2015). "In contrast, increased amount or potency of a given immunizing antigen or different models of infection or immunization have been shown to favor lower-affinity CD4+ T cell clonotypes for entry into the memory pool." (PMID 26322045, 2015). "In animals #6, #7 and #8, we observed a slight increase of Ki-67+CD4+ T cells, one or two weeks after primary infection, with the majority of proliferating cells expressing the activation marker CD8α." (PMID 25971313, 2015). "Our previous work demonstrated that Env protein is expressed in resting CD4 cells after infection, and herein we provide evidence that Nef protein is also expressed in infected resting cells concurrently with the loss of surface CD4." (PMID 26537682, 2015). "The proportions of Treg (CD4+CD25+) cells gradually increased and peaked at 10.32% of total CD4+ lymphocytes at 5 days post-infection." (PMID 26230498, 2015). "This secondary infection resulted in the generation of both effector and central memory CD4+ and CD8+ T cells demonstrating that the infection induced an effective immune response." (PMID 26178856, 2015). "Non-mac-tropic R5 envelopes (Envs) require high CD4 levels for infection contrasting with highly mac-tropic Envs, which interact more efficiently with CD4 and mediate infection of macrophages that express low CD4." (PMID 25809903, 2015). "Since healthy individuals that can effectively control the infection were tested, these data provide insights into the type of CD4 cell responses that are compatible with a controller status." (PMID 26258786, 2015). "The proportion of Th2 (CD4+IL-4+) cells remained low at 3 days post-infection but then significantly increased and reached a maximum (16.66% of total CD4+ lymphocytes) at 5 days post-challenge." (PMID 26230498, 2015). "Changes at the env region observed for X4 pseudotyped HIV-1 were reproduced at every X4 infection condition (including infections of unstimulated and stimulated PBMCs and T CD4+ cells." (PMID 26413773, 2015). "Factors found significantly associated with clustering were: infection during or after 2003, diagnosis of primary HIV infection, higher CD4 cell count, and the infection being acquired in Slovenia." (PMID 25887543, 2015). "Having a high CD4+ T cell count clearly promoted a result of incident infection (p = 0.0002; OR per additional 100 CD4+ cells, 1.125; 95% CI, 1.058–1.195)." (PMID 26230082, 2015).
infection (continued). "GITRL tg and WT mice were injected with a depleting antibody against CD4 before and early during the infection (on days-3 and day 4 p.i.;)." (PMID 25738498, 2015). "On a trouvé un lien important du point de vue statistique entre le nombre de CD4 de moins de 200 cellules/μL et l'infection par les helminthes (p = 0.05)." (PMID 26842519, 2015). "The set-point VL was around 400,000 copies/ml and the CD4 T cell count dropped to 375 cells/μl during the first year of infection." (PMID 25569444, 2015). "Overall, this increase in infection suggests that knocking down SAMHD1 in resting CD4+ T cells biases the cells toward productive infection, an observation that is confirmed by calculating the ratio of latently infected to productively infected cells." (PMID 26067822, 2015). "With respect to the changes in our adult CF population, elevations in several regulatory CD4+ subsets have been reported to occur in response to chronic inflammation and infection." (PMID 25803862, 2015). "In contrast, viruses isolated from the CSF of adults within four months of infection are uniformly poor at infecting low CD4 cells, indicating that they have been selected for replication in T cells." (PMID 25811757, 2015). "The strengths of our study relate to the homogeneity of our patient cohort with respect to treatment, stage of infection, viral load and CD4+ T cell counts." (PMID 26475133, 2015). "AVP vaccination was found to result in a polarized IFNγ CD4+ T cell response, while the individuals exposed to B. anthracis by natural infection mounted a broader cytokine response encompassing IFNγ, IL-5, −9, −10, −13, −17, and −22." (PMID 26075052, 2015). "Although this model is a skin based model it points out a potential mechanism leading to an inability to recruit an effective CD4+ T cell response during (early) infection to the site of infection." (PMID 26092382, 2015). "We observed a higher expression of IL-17 in CD4+ T lymphocytes after infection with both strains compared to media control." (PMID 26147698, 2015). "From a biological perspective, the results from our study suggest that the observed enhanced double infection rates in primary CD4+ T cells are primarily a result of only a fraction of cells that can be infected by HIV-1 regardless of titer." (PMID 26559763, 2015). "CM from a number of individuals was collected and tested for the capacity to bind DC-SIGN and inhibit HIV-1 cis- or trans-infection of CD4+ T-lymphocytes." (PMID 25793526, 2015). "Conversely, a rapid down-regulation of CD4+CD8+ double positive T (DPT) cells was observed in the challenged control group after HP-PRRSV (HuN4) infection, as previously reported." (PMID 26573719, 2015). "The exception was the infected rhesus #96065; its peripheral CD4+ T cell counts remained relatively constant during infection." (PMID 26713320, 2015). "During the long chronic phase of infection, the virus is found integrated in the genome of T lymphocytes (more than 90% are CD4+ T cells)." (PMID 26690200, 2015). "Together, the papers presented here review our current understanding of Th effector choice in infection and emphasize the importance of defining molecular pathways dictating specificity vs. diversity and stability vs. plasticity in CD4+ T cells." (PMID 25972870, 2015). "In patients with chronic HCV-2/3 infection, univariate analysis showed that CD4 count (p = 0.05) and IL28B genotype (p = 0.07) were associated with SVR." (PMID 26616669, 2015). "As the infection progressed, CD4+CD25+ cells were induced or migrated into the spleen, leading to a level similar to that of the PBS group." (PMID 25803101, 2015). "In our study of HIV-infected MSMs in PHI, we monitored longitudinal changes in CD4+ T-cell counts and viral loads over the course of the first 12 months of untreated infection." (PMID 26436092, 2015). "The HIV-2 isolates replicated in CD4+ T cells, with 15-30% of Gag + cells at day 5 post-infection (p.i.)." (PMID 25582927, 2015).
infection (continued). "Preintegration latency occurs after direct infection of resting CD4 T cells and incomplete reverse transcription or a block at steps prior to integration." (PMID 25573791, 2015). "While CD4+ T cells limit Mtb infection during the acute phase of infection, cytotoxic and IFN-γ producing CD8+ T cells seem the main protective subpopulation during the chronic phase." (PMID 25915045, 2015). "Twenty six days after infection IG infected animals showed a reduction of 62% of CD4+ and an increase of 75% in the number of CD8+ cells, and an increase in double-positive cells when compared to control." (PMID 26469517, 2015). "We show that TBEV-specific CD4+ T cell responses are polyfunctional, but the cytokine patterns after vaccination differed from those after infection." (PMID 26465323, 2015). "Higher rates of vaccine type responses and resolved infection stages in HIV-1 uninfected IDUs are related to the higher CD4+ T cell counts recorded in these study participants." (PMID 26223795, 2015). "In BLT humanized mice, HIV-1 NefP72A/P75A efficiently expanded comparable to WT HIV-1, and the level of systemic CD4+ T cell decease by HIV-1 NefP72A/P75A infection was similar to WT HIV-1." (PMID 25807049, 2015). "Cholinergic stimulation influenced several parameters of CD4 T cell function which are important in the immune response to infection." (PMID 25629518, 2015). "Nef-expressing macrophages enhance resting CD4+ T cells infection through multiple cellular and soluble interactions involving macrophages and T cells." (PMID 25835530, 2015). "The results showed that the percentages of splenic Treg cells in CD4+ T cells were suppressed on day 14 post-infection (PI) but increased on day 56 PI, while Th17 cells were increased on day 56 PI compared with normal control (NC) mice." (PMID 26599407, 2015). "Strikingly, the ratio between regulatory and inflammatory CD4+ T cells was reduced almost 16-fold in the LI LP as a consequence of infection." (PMID 25942314, 2015). "GITR triggering also boosted the helper function of virus-specific CD4 T cells already early in the infection, as was evidenced by increased IL-2 and IFNγ production, and more expression of CD40L and T-bet." (PMID 25738498, 2015). "The mechanism by which CD4 T cell responses contribute to the control of persistent infection, or how co-stimulation regulates CD4 T cell responses to infection remains incompletely defined." (PMID 25590581, 2015). "Significantly lower CD4+T cell count was found in individuals infected with CRF01_AE than in those infected with CRF07_BC infection (P<0.01), whereas viral load was significantly higher those infected with CRF01_AE than with CRF07_BC (P<0.01)." (PMID 26121491, 2015). "There have been seven transmembrane receptors identified in vitro as co-receptors for HIV/SIV that support the infection of CD4+ cells." (PMID 29061947, 2015). "Of note, IFN-γ produced by peripheral CD4+ T cells in response to recall Mtb antigens is commonly used for diagnosis of latent/active infections, detection of clinical progression and evaluation of vaccine immunogenicity." (PMID 26379242, 2015). "We examined the potential relationships between responses, time from infection, plasma viremia and CD4+ T cell count." (PMID 24472118, 2014). "The immune response to schistosomes at the early stage of infection increases the number of CD4+ Th1 cells and CD8+ T cells and leads to pathologic liver changes." (PMID 24466157, 2014). "In naturally exposed Gambians CD4+FOXP3+CD127lo Tregs during acute infection were inversely correlated with memory responses at 28 days, suggesting suppression of immune memory." (PMID 25309517, 2014). "In this study we used the rhesus recombinant anti-CD4 antibody CD4R1 to deplete RM CD4+ T-cells prior to SIVmac251 infection and investigate the sources of the increased viral burden and the lifespan of productively infected cells." (PMID 25356757, 2014).
infection (continued). "Although, we used full length HIV-1, the level of infection in primary CD4+ T cells measured at 36 hr post-infection represents a single round of the HIV-1 life cycle." (PMID 24586176, 2014). "Consistent with this, we found that infected p110δD910A mice have significantly lower numbers of CD4+CD25+Foxp3+ (Tregs) in their spleens throughout the course of infection compared to their WT counterpart mice." (PMID 24945303, 2014). "This study provides new insights into the natural history of tropism alterations for CD4+ T-cell subsets by C-HIV strains during progression from chronic to advanced stages of infection." (PMID 25387392, 2014). "gattii infection correlated with the increased CD4+ and CD8+ T cell lung infiltrates observed in these mice at the same time point." (PMID 25119981, 2014). "The loss of B cells and CD4 and CD8 T cells, and the increase in neutrophils, were especially marked 1–2 days after infection, when about 90% of CD8+ T cells disappeared from the peripheral blood." (PMID 24968319, 2014). "We found evidence of an abnormal escape of both immature CD4−CD8−CD3+FITC+ and CD4+CD8+CD3+FITC+ to the periphery during infection, as indicated by the numbers of RTEs detected in the spleen and lymph nodes at 10 dpi." (PMID 25330249, 2014). "Since monocyte/macrophage express CD4, we used CD3 to determine the infection frequency of CD4+ T-cells." (PMID 25356757, 2014). "Vaccination experiments in μMT mice also highlighted a potential problem if vaccines were to induce CD4 T cell responses, but inadequate B cell responses, with such a scenario resulting in exacerbated arthritic disease post infection." (PMID 25474568, 2014). "Initially, during infection, activated dendritic cells (DCs) modulate inflammatory leucocyte recruitment to the infection foci and the development of the T CD4+ lymphocyte response characterized by robust IFN-γ and IL-17 production." (PMID 25309905, 2014). "Infection with HIV-1 is known to induce an early decline in the number of naive CD4+, naive CD8+ and memory CD4+ T cells." (PMID 24816636, 2014). "Relative to patients with silent infections, patients with severe infections had significantly higher levels of IL-17+CD4+ cells, decreased levels of IL-17+CD8+ cells, and higher levels of IFN-γ, IL-4, IL-10, and IFN-α2 (p < 0.001 for all comparisons)." (PMID 24646014, 2014). "The Kesho Bora study shows that a significant reduction in infant infection can be achieved when pregnant women with a CD4 immune cell count of 200-500 cells/ mm3 are given a combination of three ARVs to prevent transmission." (PMID 25178042, 2014). "From the second week of infection, mice that would die or survive showed similar immune profiles, although CD4+CD25high T cells number increased earlier in mice with the worst prognosis." (PMID 24465641, 2014). "Current CD4 counts were similar between groups; however, as expected, those treated in acute/early infection had significantly higher nadir CD4 counts compared to the chronically treated group (P = 0.002)." (PMID 25340755, 2014). "Accordingly, when CD4+ T cell counts and plasma viral loads of vaccinated and control monkeys were compared in the different phases of infection, the beneficial effects of Tat/H1D/Alum immunization was evident." (PMID 25356594, 2014). "Group 4 patients controlled the infection thanks to antiviral treatment, which allowed the CD4+ T-cell response to reconstitute prior to worsening of disease." (PMID 25166270, 2014). "Our groups’ results showed that a lower than 500 cell/mm3 CD4 count was associated with HPV detection, thereby reflecting the inability of HIV-positive women’s immune systems to respond to opportunist infection." (PMID 24942545, 2014). "These antibodies can act by inhibiting various mucosal HIV-1 entry pathways such as epithelial transcytosis and by binding to the HIV-1 virus or by neutralizing the virus to prevent infection of CD4+ T cells by primary HIV-1 isolates." (PMID 24847327, 2014).
infection (continued). "Lymphocytes were harvested from peripheral tissues of individual infected animals between days 99-150 post infection and passed over selection columns to enrich for CD4+ or CD8+ subsets to further characterize the T cell memory response." (PMID 25485971, 2014). "Despite their extensive infection, little is known about how astrocytes become infected, since they lack cell surface CD4 expression." (PMID 24587404, 2014). "We find that macrophages selectively capture and engulf HIV-1-infected CD4+ T cells leading to efficient macrophage infection." (PMID 25467409, 2014). "It is well established that HIV-1 replicates efficiently in activated CD4+ T cells, whereas resting CD4+ T cells are refractory to infection with HIV-1." (PMID 25421745, 2014). "Depletion of CD4 cells from ex vivo SA cultures support these cells as the source of IFNγ at the site of infection." (PMID 25275531, 2014). "We previously reported that exposure to commensal bacteria increased productive infection in LP CD4+ T cells in vitro, likely by enhancing T cell activation." (PMID 24495380, 2014). "Patients originating from Belgium were more frequently diagnosed with a recent infection and displayed higher viral loads and CD4 counts (p<0.001)." (PMID 25003369, 2014). "Prior to infection we first showed that the proportion of each CD4+ T-cell subset and the proportion of cells expressing CCR5 and CXCR4 was similar between donors, and was consistent with the findings of previous studies." (PMID 25387392, 2014). "Despite the diverse disease outcomes, IDO inhibition induced some phenotypes that were shared by resistant and susceptible mice: the increased migration of DCs and CD8+ and CD4+ T cells concomitantly with reduced influx of Treg cells to the site of infection." (PMID 25411790, 2014). "The local expansion of SIV in both resting and activated CD4+ T cells takes place during the first week of infection." (PMID 25028990, 2014). "CD4+ T cell plasticity is important in the resolution of infections but can contribute to immunopathogenesis." (PMID 25339956, 2014). "DC-specific heparin sulfate proteoglycan Syndecan-3 cooperates together with DC-SIGN to facilitate infection of DC and transmission to CD4+ T cells and is involved in the interaction with HPV VLP." (PMID 24795724, 2014). "New evidence suggests that mucosal CD4 TRM populations differentiate at tissue sites following the recruitment of effector T cells by local inflammation or infection." (PMID 25071787, 2014). "Using AhR+/– dams, we confirmed that the presence of the AhR was required in the offspring in order for maternal treatment with TCDD to alter the CD4+ T-cell response to infection." (PMID 25051576, 2014). "The observation that VNPs have significantly lower infection of both CD4+ TCM and TSCM than do the same subsets in PPs identifies a novel, potentially crucial mechanism of protection of CD4+ T cell homeostasis in this rare subset of HIV-infected individuals." (PMID 25167059, 2014). "If MHV68 infected naïve B cells rely on CD4 T cell help for activation and differentiation, then infected extra-follicular short-lived plasma cells should be present at early times post-infection." (PMID 24789087, 2014). "Like HIV, the cell tropism of FIV alters with disease progression; while CD4+ T cells are the predominant target in the acute (early) phase of infection, in the chronic (late) phase of infection, FIV also targets CD8+ T cells and B cells." (PMID 25430586, 2014). "Further, Ad5hr infection affected the frequency of Ki67+CD4+, HLADR+ CD4+ and CCR5+ CD4+ T cells and putative CD4+ Treg cells in blood." (PMID 25203111, 2014). "Macrophages in the vaginal mucosa have been shown to be productively infected, secreting cytokines to recruit CD4+ T cells at the sites of viral entry to fuel the infection." (PMID 24612462, 2014).